GSK3B (glycogen synthase kinase 3 beta)
Diseases named in the same sentence as GSK3B in open-access papers (continued):
Sharing a sentence is not in itself a finding about the gene and the disease.
endometrial cancer (continued). "Our FACS analyses showed a G2/M arrest in endometrial cancer cells treated with GSK3β inhibitors, which prompted us to examine the expression of Cyclin B1, a cell cycle regulator that is rapidly up-regulated at G2 and degraded at mid-M-phase." (PMID 23941783, 2013). "At 10 μM, GSK3β inhibitor VIII inhibited cell growth of all six endometrial cancer cell lines tested, while only modestly affecting EM-TERT cells." (PMID 23941783, 2013). "In this study, we investigated the effects of GSK3β inhibitors on human endometrial cancer cell growth in vitro and in vivo." (PMID 23941783, 2013). "To further elucidate at which stage of G2/M the endometrial cancer cells arrest after GSK3β inhibition, we performed immunofluorescence against phospho-histone H3 (pHH3), a well-established mitotic marker." (PMID 23941783, 2013). "Intriguingly, Western Blot on active form of GSK3β (pTyr216) revealed a marked higher basal level in untreated AN3CA and ARK1 cell lines than the control EM-TERT cell line, indicating abnormal hyperactivity of GSK3β in endometrial cancer cell lines." (PMID 23941783, 2013). "RNF144B promotes phosphorylation of GSK3β in endometrial cancer." (PMID 40756570, 2025). "In endometrial cancer cell lines, GSK3β inhibitors exhibit anti-proliferative effects." (PMID 29724995, 2018). "However, the role of GSK-3β in endometrial carcinoma is still unclear; therefore, we analyzed the potential molecular mechanism of GSK-3β in endometrial carcinoma and explored its function for the diagnosis and therapy of EC." (PMID 27050373, 2016). "Our results demonstrate for the first time that GSK-3β may be a novel and important therapeutic target for the treatment of endometrial carcinoma." (PMID 27050373, 2016). "Finally, we showed in an AN3CA endometrial cancer xenograft model that GSK3β inhibition suppressed tumor growth in vivo." (PMID 23941783, 2013). "To determine whether GSK3β inhibition likewise changed gene regulation in endometrial cancer cells, we performed quantitative real-time RT-PCR on a set of genes related to PTX sensitization." (PMID 23941783, 2013). "GSK-3β inhibitor AZD1080 may be an effective drug for treating endometrial carcinoma." (PMID 27050373, 2016). "It is noteworthy that AN3CA and ARK1 endometrial cancer cell lines exhibited higher level of active form of GSK3β (pTyr216) compared to control EM-TERT cells, which may also contribute to their higher susceptibility to GSK3β inhibition." (PMID 23941783, 2013). "In endometrial cancer, NR2F1-AS1 promotes migratory potential by targeting miR-363/SOX4 and activating the PI3K/AKT/GSK-3β pathway." (PMID 40828427, 2025). "In endometrial cancer, it promotes proliferation and anti-apoptotic effects by sponging miR-363, upregulating SOX4, and activating the PI3K/AKT/GSK-3β pathway." (PMID 40828427, 2025). "WTAP is also associated with chemoresistance in hematological malignancies and endometrial carcinoma by upregulating the expression of MRP1 and P-gp and enhancing the phosphorylation of GSK3β at Ser9." (PMID 36207306, 2022). "Our work revealed that the abnormal expression of FBXL16 in Ishikawa cells led to the inhibition of GSK3β-dependent cyclin D1 degradation and ultimately the promotion of MPA resistance in endometrial carcinoma." (PMID 36106050, 2022). "Thus, metformin might promote a hyperactive state of GSK3-β in endometrial cancer cells, resulting in a further decrease in β-catenin protein and a drop in the transcription of TCF/LEF target genes, including the cell-cycle regulatory genes cyclin D1 and c-myc." (PMID 33946426, 2021). "LncRNA OGFRP1 promoted the malignant progression of endometrial carcinoma by regulating the miR124-3p/SIRT1 axis and activating the PI3K/AKT/GSK-3β pathway." (PMID 32587476, 2020). "An endometrial cancer tissues with high expression of GSK3β exhibited higher levels of LSD1, whereas the GSK3β-lowly expressing one had lower levels of LSD1." (PMID 29593255, 2018).
endometrial cancer (continued). "By using endometrial cancer cell lines, we demonstrated that PIR2/RNF144B is stabilised via phosphorylation downstream of GSK3β and this is necessary for the proliferation of endometrial cancer cells, in the absence of oestrogenic growth stimuli." (PMID 29724995, 2018). "Inhibition of GSK3β by either lithium chloride (LiCl) or specific GSK3β inhibitor VIII showed cytostatic and cytotoxic effects on multiple endometrial cancer cell lines, with little effect on the immortalized normal endometrial cell line." (PMID 23941783, 2013). "Consistently, treatment with GSK3β inhibitor VIII, a highly specific and potent inhibitor of GSK3β, also resulted in similar cell cycle arrest and growth inhibition of the endometrial cancer cell lines." (PMID 23941783, 2013). "In the current study, we explored effects of GSK3β inhibitors, lithium chloride and GSK3β inhibitor VIII (AR-A014418), on multiple human endometrial cancer cell lines." (PMID 23941783, 2013). "In addition, we can see that the endometrial cancer pathway directly related to tumor development contains three genes of QKI, CTNNA1, GSK-3b." (PMID 35068348, 2022). "Moreover, the GSK3β inhibitor LY2090314 – which has already undergone clinical testing – induced ETS1 degradation in ovarian and endometrial cancer cells, an effect blocked by MG132 in the presence of GSK3β siRNA." (PMID 34023818, 2021). "ARNT2 (Cluster 5), BRAF (Cluster 5), and PAK7 (Cluster 5) were mapped to “Renal cell carcinoma;” APC (Cluster 5), BRAF (Cluster 5), and GSK3B (Cluster 2) were mapped to “Endometrial cancer;” and APC (Cluster 5) and GSK3B (Cluster 2) were mapped to “Basal cell carcinoma” in our results." (PMID 28445522, 2017). "GSK-3β inhibitor AZD1080 inhibit endometrial carcinoma cell proliferation, migration and invasion and may be an effective drug for treating endometrial carcinoma." (PMID 27050373, 2016). "To determine whether the LiCl effect seen in the endometrial cancer cell lines was specific to GSK3 inhibition, we tested another GSK3β inhibitor, GSK3β inhibitor VIII, and found similar results." (PMID 23941783, 2013). "In addition to identifying well-known drivers, CHASM identified potential drivers not previously associated with endometrial cancer, in biologically relevant pathways: viz MTOR in the PI3K pathway and GSK-3B in the Wnt signalling pathway)." (PMID 23325621, 2013).
epilepsy (23 papers, 2014 to 2024). A brain disorder characterized by episodes of abnormally increased neuronal discharge resulting in transient episodes of sensory or motor neurological dysfunction, or psychic dysfunction. "Furthermore, GSK3β alterations do increase seizure susceptibility, and increased GSK3β activity has been evidenced in other epilepsy models." (PMID 32256316, 2020). "The expression of TREM2, PI3K, P-Akt, and GSK3β was significantly lower in the epilepsy group rats than in the CON and sham group rats, and there was no significant change in Akt expression." (PMID 35432728, 2022). "Epilepsy and AD are considered to share similar pathological hallmarks and processes, e.g., Aβ accumulation, tau protein, GSK3β, and neuroinflammation, which mutually affect each other and promote aggravation of the pathologies." (PMID 34121170, 2021). "GSK-3 inhibitors (NP031112 and NP060103) have been demonstrated to exacerbate hippocampal damage and increase seizure severity during KA-induced SE, warranting caution against targeting GSK-3β in epilepsy." (PMID 32545604, 2020). "Together, our findings reveal that the neurodevelopmental and neurodegenerative deficits in Wwox knockout mice strikingly recapitulate the key features of human neuropathies, and that targeting GSK3β with lithium ion ameliorates epilepsy." (PMID 32000863, 2020). "On the other hand, as an important drug target, GSK‐3β increases the phosphorylated tau protein, which is an essential factor in epilepsy." (PMID 31033195, 2019). "Pharmacological studies aimed at elucidating the role of GSK-3β inhibition in epilepsy showed a neuroprotective effect of GSK-3β inhibition against glutamate-induced toxicity in vitro and in vivo." (PMID 31191636, 2019). "The present study shows that both increased and decreased GSK-3β activity exacerbates seizure-induced cell death, indicating a narrow tolerance for manipulation of this pathway in epilepsy." (PMID 30237424, 2018). "There have been no genetic studies carried out to assess the contribution of GSK-3β to seizures and seizure-induced neuropathology relevant to epilepsy." (PMID 30237424, 2018). "Although GSK3β overexpression does not cause epilepsy, it significantly increases the neuronal susceptibility to seizures." (PMID 34121170, 2021). "Consequently, GSK3β should be considered as an important part of the complex mechanism linking epilepsy and AD." (PMID 34121170, 2021). "This pathway resulted as impaired in KA and electroconvulsive epilepsy models and also could promote GSK3β activation, neuronal damage, and tau phosphorylation before seizures." (PMID 32256316, 2020). "Since tau hyperphosphorylation is the main mechanism responsible for NFT formation, it has been suggested that inhibiting different tau kinases such as CDK5 and GSK3β, involved in tau hyperphosphorylation, could reduce their aggregation, observed in AD and epilepsy." (PMID 32256316, 2020). "The underlying mechanisms of tau hyperphosphorylation in epilepsy involve alteration of tau kinases like glycogen synthase kinase-3β (GSK-3β) and cyclin-dependent kinase 5 (CDK5); overactivation of both has been detected in resected tissue from refractory patients with epilepsy." (PMID 39337715, 2024). "In addition, treatment with lithium or GSK3β inhibitors suppress GSK3β activity and thus corrects behavioral phenotypes in animal models of NDDs, including ID, ASD, SZ, and epilepsy." (PMID 38568173, 2024). "The current study defined the potential role of ABP in inhibiting the development of epilepsy, indicating that ABP could upregulate TREM2 to alleviate neuronal apoptosis, by activating the PI3K/Akt/GSK-3β pathway and oxidative stress in epilepsy." (PMID 35432728, 2022). "Furthermore, inactivated (phosphorylated) GSK3β promotes CREB S133 phosphorylation that increases in human patients and animal models of epilepsy and participates in ictogenesis." (PMID 33919872, 2021).
epilepsy (continued). "Regardless of these discrepancies, GSK-3β is considered an important contributor to the development of epilepsy." (PMID 31191636, 2019). "Since the increased GSK3β-mediated CREB S133 phosphorylation participates in ictogenesis in human patients and animal models of epilepsy, these findings indicate that AMPAR antagonists may negatively regulate surface GRIA expression via GSK3β/CREB signaling pathway in responders." (PMID 33919872, 2021). "Even though GSK3β has not been demonstrated to produce epilepsy in itself, there is evidence showing that GSK3β inhibition does result in anticonvulsant activity, even after brain excitability has been altered from normal, healthy conditions into a “pro-epileptic” state." (PMID 32256316, 2020).
triple-negative breast carcinoma (23 papers, 2015 to 2026). An invasive breast carcinoma which is negative for expression of estrogen receptor (ER), progesterone receptor (PR), and human epidermal growth factor receptor 2 (HER2). "GSK3β′s role in cancer progression also offers drug development opportunities, particularly in aggressive cancers like triple-negative breast cancer, where it is linked to EMT and cancer stem cell properties." (PMID 41190025, 2025). "Importantly, we show that co-treatment with both Chk1 and GSK3-β inhibitors significantly reduces cell proliferation in four triple negative breast cancer cell lines with different mutations, whereas single treatments had only a minor effect." (PMID 31362447, 2019). "MiR-27a enhances the proliferation of triple-negative breast cancer (TNBC) cells by targeting glycogen synthase kinase-3 beta (GSK-3β), leading to the release of β-catenin and its translocation into the nucleus." (PMID 39634266, 2024). "A previous study showed that strictinin treatment modulated the PI3K/AKT/GSK3β pathway in triple negative breast cancer and blocked IL-8 mRNA expression in normal human epidermal keratinocytes." (PMID 36829604, 2023). "For example, studies have shown that GSK3B gene is a potential drug target of triple negative breast cancer, which can regulate epithelial mesenchymal transformation and tumor stem cell characteristics." (PMID 35280773, 2022). "Here we show that inhibition of both GSK3-β and Chk1 are collaborating in promoting apoptosis in breast triple negative cancer cells, thereby opening new opportunities for cancer therapy." (PMID 31362447, 2019). "Inhibition of TGF-β signaling by down-regulation of TGF-β ReceptorII and alterations in the expression of Snail, Twist, Vimentin, E-cadherin, P-Smad2, β-catenin and GSK3-β by curcumin in triple negative breast cancer cells suppressed EMT." (PMID 25786122, 2015). "We preliminarily confirmed that the mitochondrial outer membrane protein FUNDC2 may promote the development of triple-negative breast cancer through the AKT/GSK3β/GLI1 signaling axis." (PMID 37700593, 2023). "Interestingly, we found that combined enzymatic inhibition of GSK3-β and Chk1 synergizes and triggers apoptosis in triple-negative breast cancer (TNBC) cells, and therefore provides an opportunity to make more effective combination therapy with GSK3-β inhibitors in TNBC and other cancers types." (PMID 31362447, 2019). "In conclusion, Schisandrin A exhibits potential anti-triple-negative breast cancer (TNBC) effects by modulating and regulating diverse pathways, including GSK3B and IDO1, alongside its impact on the cell cycle and immune microenvironment." (PMID 42220063, 2026). "For instance, WD repeat protein 41 (WDR41) is under-expressed in triple-negative breast cancer, and methylated WDR41 positively regulates the AKT/GSK-3β/β-catenin pathway, promoting tumor proliferation, migration, and invasion." (PMID 39044262, 2024). "Given the crucial roles of GSK-3β in epithelial–mesenchymal transition (EMT), we assume that it may also be involved in tumor stemness, immune evasion, and drug resistance in triple-negative breast cancer (TNBC)." (PMID 41321870, 2025). "For example, overexpression of CCT2 could promote triple-negative breast cancer cell chemoresistance and cell migration and invasion via the AKT/GSK3β/β-catenin and XIAP/Survivin pathways." (PMID 37006287, 2023). "In addition, hsa-miR-27a-3p has been identified as an onco-miR and promotes proliferation and migration of colorectal and triple negative breast cancer cells through targeting BTG-1 and GSK3β, respectively (C. Su, Huang, Liu, Liu, & Cao, 2019)." (PMID 37533517, 2022). "GSK3β regulates EMT and CSC properties in triple-negative breast cancer." (PMID 36497426, 2022).
triple-negative breast carcinoma (continued). "Moreover, there have been many studies on GSK3B inhibitors, including Metavert molecule in PAAD, BT-000775 molecule in BRCA, BIO molecule in TNBCs (triple-negative breast cancers), AR-A014418 and SB-216763 molecules in STSs (soft tissue sarcomas), etc." (PMID 33365328, 2020).
renal cell carcinoma (21 papers, 2013 to 2025). "Association between nuclear glycogen synthase kinase-3β (GSK-3β) staining and clinicopathological characteristics in 41 renal cell carcinoma patients." (PMID 37754254, 2023). "seRNA-activated PI3K/AKT signaling can not only promote autophagy, but also accelerate angiogenesis in anaplastic ATC and renal cell carcinoma (RCC) through triggering GSK3β/ANG and GSK3β/AM pathway activation." (PMID 32278350, 2020). "The results demonstrate low miR-199a expression as a feature of advanced renal cell carcinoma, identify miR-199a as a negative regulator of GSK-3β, and suggest re-expression of pre-miR-199a as a new potential treatment of renal cell carcinoma." (PMID 26065676, 2015). "Recent studies have additionally shown that GSK3β inhibitors induce growth suppression and apoptosis in human chronic lymphocytic leukemia, glioma, colon cancer and renal cell carcinoma." (PMID 23565238, 2013). "Whether RSK4 could mediate the invasion and metastasis of renal cell carcinoma by rpS6 and GSK3β is also a new direction proposed by this study." (PMID 32209138, 2020). "Lastly, aberrant nuclear accumulation of GSK3β in renal cell carcinomas has been reported." (PMID 23565238, 2013). "Among them, the NOTCH2 gene was related to cell stemness, which could induce and regulate the occurrence and apoptosis of tumor cells; NT5E could inhibit the growth, EMT process, and AKT/GSK-3β signaling pathway of sunitinib-resistant cells in renal cell carcinoma." (PMID 38730456, 2024). "Meanwhile, research shows that Acylglycerol kinase (AGK), a newly discovered lipid kinase, could increase the nuclear accumulation of β-catenin by activating the PI3K/AKT/GSK-3β signaling pathway in renal cell carcinoma (RCC) that further potentiates the activity of TCF/LEF transcription factor." (PMID 35186189, 2022). "Moreover, inhibition of Ecto-5′-nucleotidase could depress epithelial-mesenchymal transition process and AKT/GSK-3β signal pathway in renal cell cancer." (PMID 30992388, 2019). "Klotho inhibits pro-tumoral vias, including the PI3K/Akt/GSK3β/Snail pathway, which is important for EMT, an important process in tumor invasion and migration in renal cell carcinoma and other cancers." (PMID 40004457, 2025). "Inhibition of PI3K/AKT or knockdown GSK-3b could decreased the expression of FSCN1, and then attenuated renal cell carcinoma invasion." (PMID 36085041, 2022).